MAVS (mitochondrial antiviral signaling protein)
Diseases named in the same sentence as MAVS in open-access papers (continued):
Sharing a sentence is not in itself a finding about the gene and the disease.
kidney disease (2 papers, 2023 to 2025). "This review provides novel insights into MAVS’s role and therapeutic potential in the pathogenesis of renal diseases." (PMID 37901251, 2023). "Experimental studies have focused on the pivotal role of MAVS signaling in regulating kidney disease progression, indicating the potential of MAVS as a therapeutic approach for managing kidney disease." (PMID 37901251, 2023). "This review focuses on the role of MAVS in the etiology of renal dysfunction and the pathogenesis of kidney disease." (PMID 37901251, 2023). "Herein, we summarize the structure, activation, pathophysiological roles, and MAVS-based therapies for renal diseases." (PMID 37901251, 2023). "Therefore, understanding and inhibiting MAVS and its downstream signaling pathways have significant importance in management of renal diseases." (PMID 37901251, 2023). "Taken together, these findings suggested that specific miRNAs targeting MAVS may be a potential strategy for the management of renal diseases." (PMID 37901251, 2023). "These negative regulation helps to terminate MAVS signaling and prevent prolonged inflammation immune activation, which could be used for treatment of kidney diseases." (PMID 37901251, 2023). "Here, we illustrate recent progress in comprehending the roles of MAVS in AKI, CKD, and other renal diseases, such as diabetic renal disease and hypertensive renal disease." (PMID 37901251, 2023). "To date, interactions between intestinal and kidney specific deletion of MAVS have not been validated in kidney disease, and the role of MAVS in kidney tissue await further exploration." (PMID 37901251, 2023).
neurologic disease (2 papers, 2022 to 2025). "Mice deficient in type I interferon receptors or key signaling molecules (IRF3, IRF7, or MAVS) develop neurologic disease following intraperitoneal infection, suggesting that innate immunity is likely responsible for controlling JCV in the periphery and preventing neuroinvasion." (PMID 41313001, 2025). "As aberrant ADAR3 expression has been connected to several neurological diseases, the ability of ADAR3 to alter MAVS expression and signaling should be explored." (PMID 35850307, 2022).
brain disorder (1 paper, 2025). A disease affecting the brain or part of the brain. "Of the significant reverse MR relationships, the brain disorders demonstrated associations with the increased expression of six proteins (PAMR1, MAVS, F11R, REN, GER and LEPR) and decreased expression of three proteins (TNFRSF4, BTN2A1, ENPP6)." (PMID 40456753, 2025).
cardiac diseases (1 paper, 2025). "Emerging evidence indicates that MAVS is intricately involved in the pathogenesis of heart diseases." (PMID 40040697, 2025). "Although the role of MAVS in cardiac diseases requires further explored, its significance and relevance to cardiac diseases are widely acknowledged." (PMID 40040697, 2025). "This article provides a comprehensive summary and description of MAVS research in cardiac disease, encompassing structure, expression, protein-protein interactions, modifications, as well as the role of MAVS in heart disease." (PMID 40040697, 2025). "Therefore, this article offers a brief summary of the molecular biology, protein interactions, modifications and research progress of MAVS and elucidating role of MAVS in cardiac disease to establish a scientific basis for therapeutic intervention." (PMID 40040697, 2025).
epithelioma (1 paper, 2020). "To test whether miR-122 participates in the regulation of MAVS expression, we first sought to cotransfect of miR-122, together with MAVS expression plasmid into fish epithelioma papulosum cyprini cells (EPC)." (PMID 32678830, 2020).
MAVS also shares sentences with these, for which no sentence is quoted: inflammatory bowel disease (3 papers); Aicardi-Goutières syndrome (2); B cell lymphomas (2); Insulin resistance (2); Non-alcoholic fatty liver disease (2); Parkinson disease (2); prostate carcinoma (2); rheumatoid arthritis (2); acute kidney injury (1); allergic asthma (1); Arthritis (1); calcification (1); cardiomyopathy (1); Cognitive impairment (1); cutaneous leishmaniasis (1); dyslipidemia (1); ephemeral fever (1); esophageal carcinoma (1); gastrointestinal tumors (1); Glucose intolerance (1); Herpesvirus infection (1); hypertrophic cardiomyopathy (1); immunodeficiencies (1); Kaposi's sarcoma (1); Large vessel vasculitis (1); lung adenocarcinoma (1); lung squamous cell carcinoma (1); measles (1); metabolic disorders (1); Metastatic cancer (1).
A further 16 diseases each share a sentence with MAVS in 1 paper.